KLF4 (KLF transcription factor 4)
Diseases named in the same sentence as KLF4 in open-access papers (continued):
Sharing a sentence is not in itself a finding about the gene and the disease.
cancer (continued). "Understanding the context-dependent functions of KLF4 and KLF5 and the mechanisms through which they exert their effects will be extremely helpful in developing targeted cancer therapy." (PMID 37173904, 2023). "We will discuss below how SOX2, OCT4, KLF4, and c-MYC regulate G1 dynamics in stem cells and cancer cells." (PMID 37760529, 2023). "The bioinformatic analysis of TCGA suggests that combinations of MYC and KLF4 as well as OCT4 and MYC were important for permissive cancers." (PMID 37515162, 2023). "Additionally, it was shown that lncRNA ABHD11 antisense RNA 1 (ABHD11-AS1) could recruit EZH2 to the promoter region of KLF transcription factor 4 (KLF4) gene, thereby repressing the transcription of KLF4, which might function as a cancer inhibitor to inhibit the NSCLC’s Warburg effect." (PMID 37069649, 2023). "BCSCs play an important role in cancer metastasis due to the aberrant expression of some stemness-related factors, such as CD44, SOX2, OCT4, c-MYC, KLF4, Nanog, and SALL4." (PMID 35740529, 2022). "The obtained results showed that tumors from LPC pIL-17 have a significant increase in cancer cell and CSC markers (Cd133, Klf4, Thy1, Ck19, Afp and Gpc3) when compared to tumors from LPC pEmpty." (PMID 35342340, 2022). "HIF-1 regulates expression of cancer stem cell markers like KLF4, MYC, OCT4, SOX2, and NANOG, and thus help cancer cells to survive through hypoxic crisis." (PMID 36253762, 2022). "Our work demonstrates that E2F3-induced MEX3A directly suppresses terminal differentiation regulator KLF4 to activate WNT signaling, that in turn sustains cancer cells in rapidly-dividing and undifferentiated state." (PMID 36276637, 2022). "Accordingly, IFN-I exposure induced significant upregulation of Klf4, Oct3/4, Sox2, Nanog, hes family bHLH transcription factor 1 (Hes1) and Nes, and endowed MCA205 and AT3 cancer cells with increased sphere-forming ability." (PMID 36002648, 2022). "Further, we found that the KLF4/ALDH1A1/EGF regulatory axis contributes to Cr(VI)‐induced carcinogenesis and promotes cancer cell differentiation." (PMID 36504325, 2022). "Kim and Singh (2014) reported that WA has the potential to inhibit Notch4 activation and reduce KLF4 expression and ALDH1 activity in MCF-7 and SUM159 cancer stem cells." (PMID 35740529, 2022). "Our study showed that PFK158 attenuates sphere formation, migration/invasion and KLF4 mRNA expression, and enhances the sensitivity of ALDH+CD44+ cancer cells." (PMID 35155224, 2022). "In particular, cluster 11 had high expression levels of cancer stem cell (CSC) marker genes, including NOTCH1, KLF4, CD44, EPAS1, and MYC." (PMID 36618022, 2022). "ER+ BC cells grown in coculture with DLL4+-HMVECs had higher levels of gene expression of cancer stemness-related genes (CD44, ALDH1A1, KLF4, and CD36) and PKD-1, as compared to ER+ BC cells grown in monoculture." (PMID 34168243, 2021). "cBioPortal was used to investigate the specific genetic alterations of KLF4 and IL-1β in NSCLC dataset (TCGA, Pan Cancer Atlas) with 1144 patient samples (660 LUAD + 484 LUSC)." (PMID 34440860, 2021). "Enrichment of cancer stem‐like cells was confirmed by investigating the expression of SOX2, KLF4, NANOG and OCT4 key stemness genes using real‐time PCR." (PMID 33634564, 2021). "qRT‐PCR showed that circFAT1 KD significantly inhibited the expression of the cancer stemness‐related genes, including SOX2, KLF4, MET, BMI1, CD24, OCT4, and ALDH1, in ALDHhigh SCC23 cells." (PMID 34258151, 2021). "In the meantime, SPP1 overexpression promotes the expression of KLF4, NANOG, SOX2, and BMI1, which were cancer stem cell markers." (PMID 33996808, 2021). "Although some of the studies found that miR-135 acts as an antioncogene in several cancers including OS, and this is the first report that miR-135a can inhibit OS development by targeting BMI1 and KLF4 in vitro and in vivo." (PMID 33828977, 2021).
cancer (continued). "In order to compare CpG DNA methylation in the human KLF4 gene across diverse hematologic malignancies, we analyzed publicly available reduced representation bisulfite sequencing (RRBS) data through the cancer cell line encyclopedia (CCLE)." (PMID 33659038, 2021). "Since SOX2, KLF4, and BMI1 are transcription factors which are mainly located in the nucleus of cancer cells, it was unlikely that circFAT1 regulated their expression directly." (PMID 34258151, 2021). "Treatment of vHCC with momelotinib reduced the expression of cancer stemness markers, such as CD133, KLF4, and SOX2, and decreased ALDH1 activity, suppressing tumorsphere and colony formation of HCC cells." (PMID 34199353, 2021). "Increased expression levels of LGR5, PROM1, KLF4, SOX2, and MYC in HGD and cancerous tissues support the malignant phenotype and the existence of cancer stem cells and demonstrate that they can be used to assess diagnosis and prognosis." (PMID 34452555, 2021). "The gene expression of CRC cancer stem cell markers, including SOX2, OCT4, NANOG, KLF4, ALDH1A1, and CD44, were all highly expressed in CARMA3-overexpressed cells compared to control cells." (PMID 34885061, 2021). "Krüppel-like factor 4 (KLF4) is a zinc finger transcription factor that exhibits dichotomous activity in a variety of processes during development and cancer." (PMID 32552913, 2020). "Our results also showed that the expression of cancer stem cell marker genes (e.g., MYC, NANOG, OCT4, and KLF4) was higher in C4-2B cells than that in LNCaP cells and it was markedly decreased by the silencing of SETD1A." (PMID 32629770, 2020). "On the contrary, Smad4, a cancer suppressor and an important mediator of TGF‐β1 pathway, was down‐regulated by KLF4 overexpression." (PMID 31830379, 2020). "Taken together, these studies reveal an essential role for KLF4 in the regulation of CSC properties and suggest KLF4 as a potential therapeutic target for cancer treatments." (PMID 32754274, 2020). "We further found that expression of the cancer stemness-related proteins GLUT1, ALDH1, OCT4, and KLF4 were upregulated in the presence of MDSCs and dose-dependently downregulated after treatment with Rg3." (PMID 33091036, 2020). "The levels of cancer stemness-related genes (ABCG2, BMI1, NANOG, KLF4, and OCT4) mRNA and proteins (ABCG2, Oct4, Bmi-1, and CD44) expression were downregulated with treatment of STF-31 in HBx-expressing MHCC-97H cells." (PMID 32168902, 2020). "Dual-luciferase reporter assays demonstrated that Kruppel-like factor 4 (KLF4), expression of which is highly correlated with cancer stemness, was a target of miR-7-5p." (PMID 33052880, 2020). "On the basis of previous studies of NANOG regulators in various cancers, we chose the following protein regulators for further analysis: AGR2, KLF4, NOTCH1, OCT4, and SOX2." (PMID 32733958, 2020). "microRNA-7 (miR-7) has been described as a negative regulator of several proteins involved in cancer, such as YY1 and KLF4." (PMID 33194748, 2020). "Mice with intestinal epithelium-specific deletion of Klf4 (Klf4ΔIS) treated with AOM and DSS developed significantly more adenomatous polyps and carcinomas in situ in comparison to treated control Klf4fl/fl mice." (PMID 33266506, 2020). "We engineered stable expression of GFP‐KLF4 MDA‐MB‐231 and evaluated the inhibitory effect for 422 anti‐cancer compounds on KLF4 expression levels." (PMID 33231937, 2020). "Thus, blocking KLF4 could enhance cancer cell death and thereby benefit cancer therapy." (PMID 33231937, 2020). "ALDH+CD44+ cancer cells transfected with siPDK4 exhibited lower expression of OCT4, KLF4, and BMI1 genes at both mRNA and protein levels." (PMID 32390009, 2020). "SOX2 and OCT4, along with other induced pluripotent stem cell markers KLF4, NANOG, and c-MYC, regulate stemness in CSCs and have been used them to characterize CSCs in other cancer types." (PMID 33147716, 2020).
cancer (continued). "KLF4 enhances the expression of survival proteins hTERT and HMGB1 (high mobility group box 1) which sensitizes cancer cells to cisplatin cytotoxicity." (PMID 33266506, 2020). "We also see CTNNB1, KLF4, HIF1A, and MYC as particularly important across many cancers as well as evidence to suggest substantial cross-talk and perhaps overlap." (PMID 33106165, 2020). "Our work points to the synergism between KLF4 and PARP1 in tumorigenesis and cancer therapy, which provides a potential new therapeutic strategy for killing BRCA1‐proficient triple‐negative breast cancer cells." (PMID 33231937, 2020). "CSCs, depended on cancer types, occupied different markers, such as, SOX2, CD133, epithelial cell adhesion molecule (EpCAM), CD166, CD24, CD29, Lgr5, Kruppel-like factor 4 (Klf4) and ALDH." (PMID 30962766, 2019). "Krüppel-like factor 4 (KLF4), a member of the zinc finger transcription factor family inhibits cancer EMT and metastasis via transcriptionally downregulating CAV-1 expression by binding directly to the promoter region of the gene." (PMID 31146503, 2019). "It has been widely reported that the epithelial-to-mesenchymal transition (EMT)- and stemness-related genes including Slug, KLF4, SOX2, OCT4, and NANOG are overexpressed in human cancers and confer CSCs traits." (PMID 31526394, 2019). "By extending the bridges of our sub-network with the literature survey results, we confirmed the oncosuppressor model of miR-148a through inhibition of cancer stemness by targeting SMAD2 in HCSC, AKT2 and KLF4." (PMID 30944375, 2019). "Studies have shown changes in the expression of MUTYH, KLF6, KLF4 and WNT1 genes in various cancers." (PMID 31724937, 2019). "Krüppel-like factor 4 (KLF4) is a transcription factor and plays a vital role in cancer initiation and development." (PMID 31969824, 2019). "Next, to assess the effect of DFX and CDDP on cytotoxicity and expression of stemness markers in human cancer cell lines, we used HSC-2 cells and OE33 cells, which express similar stemness markers (Nanog, Sox2, Oct3/4, Klf4, c-Myc) as ES cells." (PMID 30717462, 2019). "OCT4 is a master transcription factor that regulates the pluripotency of pluripotent stem cells and cancer stem cells along with other factors, including SOX2, KLF4, and C-MYC." (PMID 30287838, 2018). "The results revealed the expression of CD44, CD133, OCT-4, KLF4 and ABCG2 in the sphere forming cells and verified that cancer stem cells displaying the stemness properties were successfully isolated." (PMID 29559853, 2018). "PRMT5 knock down or inhibition in different cancer cell lines results in increased KLF4 ubiquitylation and turnover, highlighting the crucial role played by PRMT5 in KLF4 protein stability." (PMID 30613353, 2018). "Proliferation and invasion of cancers were increased by FOXC1 by mediating NF-κB, MST1R and KLF4 expression." (PMID 29552326, 2018). "This implies that through OCT4, KLF4, NANOG, and SOX2 alteration, KRT19 regulates cancer stem cell reprogramming efficiency in KU-CSLCs." (PMID 29747452, 2018). "Results of “ChEA 2016” analysis for 96 ≪stemness genes≫ showing elevated expression in TAMRA+ Krebs-2 carcinoma cells relative to TAMRA− cells, with regard to enrichment with SOX2/OCT4/POU5F1/NANOG/KLF4/c-MYC binding sites." (PMID 30505319, 2018). "In fact, the pluripotent cell markers OCT4, SOX2, Klf4 and NANOG have been shown to be expressed in certain cancer cell types and to play an important role in oncogenesis." (PMID 28103575, 2017). "Many stem-like cells commonly overexpress markers such as NANOG, OCT-4, SOX-2, KLF-4 and C-MYC, where these genes play important roles in the regulation of self-renewal and tumorigenicity in CSC populations of several cancer types." (PMID 29069808, 2017).
cancer (continued). "We also detected upregulation of genes involved in cancer metastasis and cancer stemness (FOXC2, SNAI2, CXCRs, and IGF1), cell stemness (NANOG, POU5F1, and KLF4), metalloproteinases (MMP7, MMP10, and MMP13), and angiogenic factors (IL-8 and S1PR1)." (PMID 28423353, 2017). "KLF4 and LIN28A, which are known as important cancer stem cell factors, were also increased in expression." (PMID 26675549, 2016). "Hypoxia can induce stem cell markers such as octamer-binding transcription factor 4 (OCT4), NANOG, SOX2, kruppel-like factor 4 (KLF4), c-MYC, and microRNA-302 in 11 cancer cell lines including HCC cells through hypoxia-inducible factor (HIF)." (PMID 27050147, 2016). "Thus, this third network corroborates our recent hypothesis and underlines the fact that this microRNA, repressing some core pluripotency factors such as OCT4 and KLF4, is crucially involved in the modulation of the differentiation pathway progression of cancer stem cells." (PMID 26880947, 2016). "In cancer cells, we analyzed the invasion-related expression of NFI-C, KLF4, and E-cadherin using GEO data." (PMID 25879941, 2015). "NFI-C overexpression increased the transcription of KLF4 and E-cadherin mRNAs, which play an important role in the MET of cancer cells." (PMID 25879941, 2015). "We found that along with KLF4 suppression, p110δ, a catalytic subunit of PI3K in cancer, Akt and mTOR (another identified target of miR-7) were significantly down-regulated in PC3-miR-7 cells and its derived xenografts." (PMID 26172296, 2015). "Thus, the expression and role of KLF4 may vary according to cancer location." (PMID 25060774, 2014). "In cancer-related EMT as well as in EMT processes that contribute to the reprogramming route, KLF4 is a potent inducer of epithelial differentiation and antagonizes the switch to a mesenchymal phenotype." (PMID 24429391, 2014). "Two related transcription factors with known roles in cancer, Sp1 and KLF4, bind to the SLC4A7 promoter, exerting opposite functions: Sp1 represses and KLF4 activates SLC4A7 transcription." (PMID 24795638, 2014). "On the other hand, EMT confers cancer cells with stem cell properties, a finding that apparently contrasts with the indispensable MET step as initiated by KLF4 during somatic reprogramming." (PMID 24429391, 2014). "We therefore investigated the CpG methylation pattern of NANOG (also known as NANOG1), OCT4, SOX2, KLF4 and c-MYC in human cancer cell lines by bisulfite sequencing approach." (PMID 24023739, 2013). "It has been demonstrated that OCT4, SOX2, c-MYC, LIN28, NANOG and KLF4 are required for ESC self-renewal and pluripotency and are upregulated in some aggressive cancers and in CSCs." (PMID 24040120, 2013). "Further study is required to determine the precise role of KLF4 in HCC and in other human cancer types." (PMID 23599755, 2013). "Similar to the inactivation of KLF6, KLF4 was shown to undergo promoter methylation and LOH in several cancer types." (PMID 22937066, 2012). "Oct4 and Nanog are exclusively expressed in embryonic stem cells, Nestin is expressed in pluripotent neural stem cells, while KLF4, c-myc, and genes of Notch, SHH, and WNT pathways are expressed in TICs of a variety of cancers." (PMID 23185379, 2012). "For example, expression of SLUG/SNAI2, TWIST, CD146 and Kruppel-like factor 4 (KLF4), which promote EMT and invasion, can drive cancer cells to express the CD44+/CD24−BCSC markers and exhibit BCSC phenotypes." (PMID 24977105, 2012). "Lowered expression of KLF4 and CARD 10 were observed when the expression levels of all AA and CAU women cancer cell lines were compared." (PMID 17472751, 2007).
cancer (continued). "The comparison of the individual relative densities of cancer cells in both cell line models between AA and CAU women revealed altered expression in 5 of the 14 potential biomarkers (Atp1b1, CARD 10, KLF4, Spint2, and Acly)." (PMID 17472751, 2007). "Further, SOX2, KLF4 and c-MYC are particularly important in regulating migration and invasion, often through pathways related to EMT, with implications in both development and cancer metastasis." (PMID 40019880, 2025). "To verify the reverse Warburg state along with the stemness characteristics, we explored the expression of the reprogramming factor KLF4 that essentially contributes to PDAC development and cancer stemness and has been recently shown to be substantially associated with this metabolic phenotype." (PMID 40508207, 2025). "This manuscript thus defines the importance of circRNA/miRNA axes in regulating KLF4 pleiotropic functions in cancer cells at a novel epigenetic level not yet reported thus far." (PMID 40863723, 2025). "Crucial stemness genes such as KLF4, OCT-4, SOX2, NANOG, and C-MYC, which are important regulators of pluripotency and the capacity for self-renewal in CSCs, were expressed in cancer cells exposed to 5-FU in comparison to both spheroids and their parental population." (PMID 40251609, 2025). "Furthermore, we discovered that a low dose of NU7441 significantly reduced CSC enrichment in drug-resistant cancer cells, as shown by decreased expression of key markers of CSCs (ALDH1A1, KLF4, CD133, Nanog, and SOX9) and diminished sphere formation ability." (PMID 41272697, 2025). "The KLF family of transcription factors, including both KLF4 and KLF6, have a well‐established role in cancer progression, and we showed direct regulation of CFTR by KLF5 in airway epithelial cells where this factor has a critical role in wound repair and innate immunity." (PMID 40785146, 2025). "OCT4, KLF4, SOX2, c‐MYC and other stem cell reprogramming factors play key roles in inducing stem cell formation, and many studies have shown that they can also promote the occurrence of CSCs in cancer and up‐regulate the expression of CSC markers." (PMID 40717222, 2025). "Studies have shown that KLF4 activity can be modulated by exogenous drugs, indicating novel therapeutic approaches for cancer treatment." (PMID 39995670, 2025). "In addition, Klf4 has been shown to be a downstream target of STAT328, and STAT3 plays a key role in regulating properties and functions of cancer stem cells." (PMID 38509141, 2024). "Furthermore, the high CBLL1 expression observed in the tumourspheres was accompanied by the upregulation of other established cancer stem cell markers, including LGR5, NANOG, SOX2, KLF4 and c-MYC mRNA levels." (PMID 38339195, 2024). "KLF4 and ZBTB16 are the two common downregulated TFs in the three types of cancer that might control key overregulated TFs and DEGs, and therefore, their expression must be controlled by key overregulated TFs during the tumorigenic process." (PMID 39228892, 2024). "Stemness, known as the self-renewal capacity of cancer stem cells, is regulated by many signaling pathways, including TGF-β, Hedgehog, Wnt, Notch, and FGF, and transcription factors, including NANOG, OCT4, SOX2, KLF4, and c-MYC." (PMID 39516821, 2024). "These cancer cells that have undergone EMT become more invasive and metastatic due to the presence of self-renewal EMT-mediating transcription factors such as Snail, Zebi, SOX2, KLF4, and many others which were discussed extensively before." (PMID 39403386, 2024).